GATA6 (GATA binding protein 6)
Diseases named in the same sentence as GATA6 in open-access papers (continued):
Sharing a sentence is not in itself a finding about the gene and the disease.
colon carcinoma (continued). "In addition, exogenous expression of LGR5 only partially rescues the tumorigenicity of colon cancer cells in which GATA6 was knocked down." (PMID 26387746, 2015). "Moreover, we show that GATA6-mediated activation of REG4 enhances the growth of colon cancer cells under adherent conditions and is required for their tumorigenicity." (PMID 26387746, 2015). "Thus, reduced miR-363 expression in colon cancer cells may contribute to the upregulation of GATA6 and consequently of REG4." (PMID 26387746, 2015). "Within the top 20 TFs that showed high correlation between their own CNV and expression, we observed known colon cancer drivers ZNF703 and SMAD4, as well as IRF2 and GATA6, whose DNA aberrations are likely oncogenic." (PMID 41114645, 2025). "We performed chromatin immunoprecipitation (ChIP) of MLL1 in Ls174T and DLD1 colon cancer spheres, in which knockdown of MLL1 decreased the mRNA expression of GATA6." (PMID 35064075, 2022). "The human shMLL1 colon cancer cells showed a decrease of the expression of FOXA1 and the GATA4 colon homolog GATA6, which we had identified as Mll1-regulated genes in murine β-catGOF; Mll1−/− stem cells." (PMID 33349639, 2020). "Cooperation between the GATA6/LGR5 and GATA6/REG4 pathways plays an important role in the tumorigenicity in colon cancer cells." (PMID 33489872, 2020). "We subsequently examined the expression levels of GATA6 protein and REG4 mRNA in colon cancer cell lines by immunoblotting and qRT-PCR analyses, respectively." (PMID 26387746, 2015). "It would therefore be intriguing to assess the role of the GATA6/REG4 and GATA6/LGR5 pathways in the properties of colon cancer stem cells." (PMID 26387746, 2015). "In the present study, we identified REG4 as a novel target gene of GATA6 and showed that GATA6-mediated activation of REG4 expression is essential for the growth of colon cancer cells under adherent conditions in culture and their tumorigenicity in vivo." (PMID 26387746, 2015). "GATA6 has been shown to be misexpressed in CRC cells from the earliest stages of dysplasia continuing to late metastatic lesions, pointing to a crucial role in the pathogenesis and progression of colon cancer." (PMID 27902469, 2017). "We have recently reported that knockdown of LGR5, in contrast to knockdown of GATA6, does not significantly affect the growth of colon cancer cells cultured under adherent conditions." (PMID 26387746, 2015). "In conclusion, our findings demonstrate that GATA6 simultaneously induces the expression of genes essential for the growth (REG4) and clonogenicity (LGR5), and that cooperation between the GATA6/REG4 and GATA6/LGR5 pathways is important for the tumorigenicity of colon cancer cells." (PMID 26387746, 2015). "In contrast to metaplasias of the proximal gastrointestinal tract, GATA-4 is not present in colon tumors, whereas GATA-6 and Ihh are moderately expressed in colon adenomas, but to a much lesser extent in carcinomas." (PMID 18405344, 2008). "MicroRNA (miR)-363 suppressed the translation of GATA binding protein 6 (GATA6), which functioned as a transcriptional factor to induce REG4 and leucine-rich repeat-containing G-protein coupled receptor 5 (Lgr5) expression essential for the growth of colon cancer cells under adherent conditions." (PMID 36172286, 2022). "Also in HT29 colon cancer cells miR-196b-5p transfection led to a decrease of pL-G6-3′UT and pL-196TS reporter activity, albeit to a lesser extent with respect to HCT116 cells, probably because of the higher expression levels of endogenous miR-196b and GATA6." (PMID 27902469, 2017). "Moreover, we have recently reported that LGR5 is a transcriptional target of GATA6 and plays important roles in the clonogenicity and tumorigenicity of colon cancer cells, but does not affect their proliferation under adherent conditions." (PMID 26387746, 2015). "In the same experiments, no significant changes in mRNA levels of GATA6 were observed both in HCT116 and HT29 colon cancer cells." (PMID 27902469, 2017).
colon carcinoma (continued). "We have recently reported that GATA6 induces the expression of the intestinal stem cell marker LGR5 and enhances the clonogenicity and tumorigenicity of colon cancer cells, but not the growth of these cells cultured under adherent conditions." (PMID 26387746, 2015). "Suppression of GATA6 or LGR5 expression attenuates the tumorigenicity of colon cancer cells in nude mice, whereas decreased expression of LGR5, but not GATA6, does not significantly affect the growth of these cells cultured under adherent conditions." (PMID 26387746, 2015). "Our results suggest that histological tumor grade does not significantly correlate with the level of expression of GATA-6 in cancer cells, although earlier in vitro studies have suggested that GATA-6 expression is strongest in the most undifferentiated colon carcinoma cells." (PMID 18405344, 2008).
ovarian carcinoma (17 papers, 2009 to 2025). A malignant neoplasm originating from the surface ovarian epithelium. "In ovarian cancer loss of GATA4 precedes loss of GATA6 expression and candifferentiate between histological subtypes." (PMID 26953528, 2016). "Loss of GATA6 expression has been found in ovarian cancer and has been associated withhypoacetylation of histones H3 and H4 and loss of H3K4me3 at the promoter region (Ref.90)." (PMID 26953528, 2016). "Previously, the loss of GATA4 and GATA6 in ovarian cancer and epithelial cells was demonstrated to be by the mechanism of hypoacetylation of histones H3 and H4 and loss of histone H3/lysine K4 trimethylation at their promoters." (PMID 19649254, 2009). "GATA4 and GATA6 were found to be frequently lost in ovarian cancer, and the loss is proposed to account for dedifferentiation of the cancer cells." (PMID 19649254, 2009). "A reduced GATA6 gene dosage as in GATA6 (+/−) mice led to an increased pre-neoplastic changes and inclusion cysts in the ovaries, suggesting the loss of GATA6 contributes to ovarian cancer development." (PMID 19649254, 2009). "On the other hand, GATA6+ macrophages can become tumor-associated macrophages to contribute to tumor progression, as deletion of peritoneal macrophages reduces tumor progression and peritoneal metastasis in ovarian cancer." (PMID 39192982, 2024). "Interestingly, such chromosomal instability was reported to arise from GATA6 loss in ovarian cancer cells." (PMID 34944784, 2021). "Loss of GATA6 is common in ovarian cancer and may lead to de-differentiation of ovarian epithelial cancer cells and increased occurrence of aneuploidy." (PMID 26498761, 2015). "GATA4 and GATA6 are often lost in ovarian cancer cells, and it is speculated that the loss of these developmentally important transcription factors may be the underlying mechanism of dedifferentiation." (PMID 19649254, 2009). "Thus, loss of GATA4 appears to be more prevalent than loss of GATA6 in ovarian cancer." (PMID 19649254, 2009). "Recently, in a study, the functional mechanism of GATA6 in ovarian cancer was elucidated, and GATA6 was found to target miR-10a-5p, which were negatively correlated with each other." (PMID 41514651, 2025). "GATA6 has been described as an independent prognostic marker in ovarian cancer and plays a key role in the differentiation and invasion of tumor cells." (PMID 36239104, 2022). "The observations from human ovarian cancer tissues suggests that loss of GATA4 expression often precedes the loss of GATA6, and the loss of GATA6, correlated with the loss of Dab2, associates with epithelial morphological transformation." (PMID 19649254, 2009). "One striking feature of GATA4 and GATA6 staining is that though GATA4 and GATA6 are lost in most ovarian cancer (predominantly serous subtype), carcinomas of the mucinous subtype are mostly GATA4- and GATA6-positive." (PMID 19649254, 2009). "We further investigated the expression of GATA4 and GATA6 in ovarian surface epithelial lesions and histological subtypes of ovarian carcinomas by immunostaining." (PMID 19649254, 2009). "GATA6 expression is related to poor prognosis in ovarian cancer." (PMID 33315534, 2021). "A decrease in GATA6 expression was observed in colon and ovarian carcinomas as well." (PMID 22672670, 2012). "Recent studies suggest the loss of the transcription factor GATA6 and GATA4 in ovarian cancer may account for the loss of epithelial characteristics and may be the underlying mechanism of “dedifferentiation” of ovarian cancer cells." (PMID 19649254, 2009). "Expression of GATA4 and GATA6 in ovarian cancer histological subtypes." (PMID 19649254, 2009).
ovarian carcinoma (continued). "The loss of GATA4 precedes the loss of GATA6 (and Dab2), similar to the observation in the pre-neoplastic ovarian epithelia adjacent to ovarian carcinomas, where GATA4 is often lost prior to GATA6." (PMID 19649254, 2009). "Likewise, H3K27ac modification around the GATA6 and DAB2 loci was reduced in ovarian cancer cell lines." (PMID 37779141, 2023). "Previously, both GATA4 and GATA6 were observed to be strongly expressed in primary ovarian surface epithelial cells but absent in cultured ovarian cancer cells by both Western blot to examine the protein or Northern blot to measure mRNA." (PMID 19649254, 2009). "Both GATA4 and GATA6 proteins are expressed in ovarian surface epithelial cells but absent in most ovarian cancer cells." (PMID 19649254, 2009). "Dab2 was also found lost in ovarian cancer, correlating with the absence of GATA6 and morphological transformation." (PMID 19649254, 2009). "Next, to validate whether the downregulated genes, such as MAF, GATA6, and DAB2, are affected by epigenetic dysregulation, we treated ovarian cancer cell lines with a pan-HDAC inhibitor, TSA, which mechanistically augments transcriptionally active histone modification." (PMID 37779141, 2023). "While GATA4 and GATA6 staining are absent or greatly reduced in most ovarian carcinomas." (PMID 19649254, 2009). "Negative GATA6 and positive GATA4 exist only in rare cases of ovarian carcinomas." (PMID 19649254, 2009).
endometriosis (16 papers, 2014 to 2025). The growth of functional endometrial tissue in anatomic sites outside the uterine body. "SF-1 and GATA6 are pivotal for initiating cascade reactions linked to steroidogenic proteins and enzymes, ultimately contributing to the development of endometriosis." (PMID 40290121, 2025). "Several studies have reported elevated levels of GATA6 concomitant with loss of GATA2 in endometriosis." (PMID 39443360, 2024). "In the present study, we examined the role of GATA6+ peritoneal macrophages on endometriosis-associated hyperalgesia using mice with a specific myeloid deficiency of GATA6." (PMID 39192982, 2024). "GATA6+ residential macrophages act to sustain local inflammation in the peritoneum and sensitivities in the neurons, reflecting endometriosis-associated hyperalgesia." (PMID 39192982, 2024). "Lastly, we assessed how GATA6 deficiency affects the progression and growth of endometriosis lesions." (PMID 39192982, 2024). "We next performed the von Frey test to examine the abdominal and hind paw retraction threshold to determine whether loss of GATA6+ LPM affects endometriosis-associated hyperalgesia." (PMID 39192982, 2024). "In ectopic endometrial stromal cells, the overexpression of GATA6 resulting from its hypomethylation, limits the ability to decidualize and has been associated with the transformation of endometrial stromal cells into estrogen-producing endometriosis-like cells." (PMID 40792071, 2025). "In the same line, the cooperation between GATA6 and SF-1 is reported to be sufficient for endometriosis development and persistence." (PMID 40792071, 2025). "According to a recent study, GATA6 plays an essential role in the acquisition of endometriosis phenotype by endometrial stromal cell (ESC)." (PMID 40792071, 2025). "First, the TET3 OE macrophages in human endometriosis lesions were of embryonic origin but lost GATA6 expression due to reprogramming by the disease microenvironment." (PMID 39141428, 2024). "Intriguingly, after entering endometriosis lesions, these LPMs lose their signature expression of GATA6, consistent with reprogramming by the disease microenvironment." (PMID 39141428, 2024). "We also observed that the GATA protein binding 6 (GATA6) was significantly decreased in the endometriosis group relative to normal cells on days 0, 2, 4, 6, and 8 of EPC treatment." (PMID 38402336, 2024). "In the present study, we used a mouse model of endometriosis to study the role of GATA6 resident macrophages following the resolution of inflammatory stimuli (lesion induction)." (PMID 39192982, 2024). "Most prior studies demonstrating elevated GATA6 in endometriotic tissues have relied on transcript level analyses whereas information related to GATA6 protein expression in endometriosis has been comparatively sparse and sometimes contradictory." (PMID 39443360, 2024). "This is consistent with the findings from mice where embryonic-derived LPMs stopped expressing GATA6 after infiltrating endometriosis lesions." (PMID 39141428, 2024). "On the opposite, GATA6 was found to be methylated and inactive in eutopic endometrium stromal cells, while was active and unmethylated in endometriosis stroma." (PMID 36612107, 2022). "Over-expression of GATA6 in endometriosis resulted in changes in the expression of hormone receptors—reduction of ERα and PR, and stimulation of ERβ." (PMID 36612107, 2022). "The epigenetic regulation (DNA methylation) of genes GATA2 and GATA6 has been noticed in endometriosis." (PMID 36612107, 2022). "Epigenetic changes in these genes, with downregulation and hypermethylation of GATA2 and hypomethylation and activation of GATA6, have been postulated to be involved in progesterone resistance and altered estrogen responses in endometriosis." (PMID 28125717, 2017). "GATA-binding factor-6 (GATA6) serves as a biomarker for endometriosis induction." (PMID 40290121, 2025).
endometriosis (continued). "Additional tissue-level studies will be required to confirm whether abnormal levels or patterns of GATA6 expression are features of endometriosis and other gynecologic disorders." (PMID 39443360, 2024). "Besides its essential role in embryonic development, GATA6 plays a key role in endometriosis and regulates steroidogenic genes." (PMID 37700285, 2023). "In addition, some identified hub genes of the EC (TAGLN, GATA6, CDH3, CLU, COL8A1, MYH11, MYOCD) and EU (CXCL13, DDK-1, KLF4, CYP2E1, CYP4B1 and PROK1) have been reported be associated with endometriosis." (PMID 34522169, 2021). "GFP+ macrophages could be easily detected in lesions, suggesting that LpM infiltrate endometriosis lesions and lose expression of GATA6, consistent with a change in phenotype within the lesion microenvironment." (PMID 33536334, 2021). "The significant differences in DNA methylation that we detected for genes such as GATA6 may also be suitable for use as a marker for endometriosis." (PMID 24603652, 2014). "Therefore, GATA6+ LPM might be favorable toward sustaining local inflammation in the peritoneum and sensitivities in the neurons, reflecting potentially endometriosis-associated pain during the process of resolution of inflammatory stimuli." (PMID 39192982, 2024). "Moreover, we suggest that GATA2 and GATA6, as target TFs of the miR-200 family, might be involved in the pathogenesis of endometriosis together with the miR-200 family." (PMID 29357938, 2018). "We investigated infiltration of LpM into endometriosis lesions using dual immunodetection for F4/80 (red) and the transcription factor GATA binding protein 6 (GATA6; LpM marker, green)." (PMID 33536334, 2021). "The more important experiment will be to address the methylation status and expression of GATA6 and NR5A1 in the eutopic endometrium of women with endometriosis." (PMID 24603652, 2014). "GATA6, which is hypomethylated and abundant in endometriotic cells, potently blocked hormone sensitivity, repressed GATA2, and induced markers of endometriosis when expressed in healthy endometrial cells." (PMID 24603652, 2014). "The GATA6 alone is essential in endometriosis pathogenesis but not sufficient to confer an endometriosis phenotype." (PMID 40792071, 2025). "We scored GATA2, GATA6, and PGR IHC in endometriosis biopsies from 18 patients." (PMID 39443360, 2024). "This reduction in GATA2 expression does not lead to a detectable increase in GATA6 expression in endometriosis." (PMID 39443360, 2024). "We only examined macrophage infiltration in the lesion on days 21 and 42, as lesion number, endometriosis-associate hyperalgesia, cytokine levels in the peritoneal cavity, and TRPV1, SP, and CGRP expression in the DRG were not altered by GATA6 deficiency until day 7 in Gata6f/f and MacGata6 KO mice." (PMID 39192982, 2024). "We find that while GATA2 expression is lost in the stromal cells of endometriosis and EAH/EIN, we detect no corresponding increase in GATA6." (PMID 39443360, 2024). "In human endometriosis lesions, TET3 OE macrophages were predominantly found in 2 subpopulations that expressed some markers of “tissue-resident macrophages/PMs,” but did not express GATA6, a signature marker of LPMs of embryonic origin." (PMID 39141428, 2024).
pancreatic ductal adenocarcinoma (16 papers, 2008 to 2026). An infiltrating adenocarcinoma that arises from the epithelial cells of the pancreas. "Reduced level of expression of GATA-binding protein 6 (GATA6), the expression of which is associated with the basal-like chemoresistant subtype of pancreatic ductal adenocarcinoma was found in the latter ones." (PMID 34834402, 2021). "GATA6, a transcription factor that controls tumor differentiation and immune escape, has been proposed as a pancreatic ductal adenocarcinoma (PDAC) subtyping marker and a predictor of chemotherapy response." (PMID 40699746, 2025). "This dualistic nature of GATA6, serving either as an oncogene or a tumor suppressor, is evident even within the same cancer type, as seen in pancreatic ductal adenocarcinoma." (PMID 39456519, 2024). "This study underscores GATA6’s role in distinguishing classical and basal-like pancreatic ductal adenocarcinoma (PDAC) phenotypes." (PMID 38733987, 2024). "The role of GATA factors in cancer has gained increasing attention recently, but the function of GATA6 in pancreatic ductal adenocarcinoma (PDAC) is controversial." (PMID 27325420, 2017). "At the very least, the upregulation of Wnt activity mediated by GATA6 dependent repression of DKK1 further supports the view that GATA6 is an oncogene in pancreatic ductal adenocarcinoma." (PMID 21811562, 2011). "Recurrent copy number gain of GATA6 has recently been identified in pancreatic duct adenocarcinoma (PDAC) cell lines and xenografts." (PMID 21811562, 2011). "In pancreatic ductal adenocarcinoma, EZH2 silences GATA binding protein 6 (GATA6), an epithelial differentiation-related protein, through epigenetic modification, and participates in the transformation of pancreatic ductal adenocarcinoma to a subtype prone to metastasis." (PMID 40028035, 2025). "GATA6 promotes epithelial phenotypes and limits epithelial-to-mesenchymal (EMT) transition in pancreatic ductal adenocarcinoma (PDAC)." (PMID 41651844, 2026). "The amplification or transcriptional upregulation of GATA6, as well as activation of the WNT signaling pathway, can improve the overall survival rate of human pancreatic ductal carcinoma (PDAC) at advanced malignant stages." (PMID 40657383, 2025).